DNMT1 (DNA methyltransferase 1)
Diseases named in the same sentence as DNMT1 in open-access papers (continued):
Sharing a sentence is not in itself a finding about the gene and the disease.
chronic kidney disease (2 papers, 2018 to 2025). Impairment of the renal function secondary to chronic kidney damage persisting for three or more months. "Upregulation of DNA methylation and DNMT1 expression have been also observed in the kidneys of chronic kidney disease and diabetic kidneys." (PMID 30397232, 2018). "A seminal study in the field of epigenetics and chronic kidney disease (CKD), published in 2010, demonstrated that methylation of the promoter of Rasal1—a gene encoding a Ras inhibitor—by the DNA methyltransferase DNMT1 activates renal fibroblasts and promotes renal fibrosis." (PMID 40186651, 2025).
chronic obstructive pulmonary disease (2 papers, 2020 to 2022). A chronic and progressive lung disorder characterized by the loss of elasticity of the bronchial tree and the air sacs, destruction of the air sacs wall, thickening of the bronchial wall, and mucous accumulation in the bronchial tree. "For instance, HDAC2 and DNMT1 have significant roles in chronic obstructive pulmonary disease (COPD) progression." (PMID 33173052, 2020).
congenital myopathies (2 papers, 2022). "Indeed, a study conducted on patients with congenital myopathies identified over 3500 differentially methylated nuclear genes and an increase in DNA methyltransferase 1 (DNMT1) expression." (PMID 35216315, 2022).
Crohn disease (2 papers, 2018 to 2022). A gastrointestinal disorder characterized by chronic inflammation involving all layers of the intestinal wall, noncaseating granulomas affecting the intestinal wall and regional lymph nodes, and transmural fibrosis. "Furthermore, we noted consistent patterns of dysregulation of DNMT1 and TET3, an enzyme that initiates the demethylation of DNA22, between KO mice and variously diseased human GI tissue, including colon/anal cancers and Crohn’s disease." (PMID 29700293, 2018).
cryptorchidism (2 papers, 2015 to 2020). The failure of one or both testes of a male fetus to descend from the abdomen into the scrotum during the late part of pregnancy. "Sperm deformities and cryptorchidism were observed, which was associated with raised Dnmt levels (Dnmt1, Dnmt3a, Dnmt3b)." (PMID 32398147, 2020).
cyst (2 papers, 2020 to 2022). A sac-like closed membranous structure that may be empty or contain fluid or amorphous material. "Another two compounds that reduced cyst swelling without major effects on viability were the ROCK 1/2 inhibitor GSK-269962A and the DNMT1 inhibitor 5-azacytidine." (PMID 32144367, 2020).
diabetic macular edema (2 papers, 2023). "According to a recent clinical study on patients with diabetic macular edema, patients who were insensitive to the anti-VEGF response had significantly higher levels of DNMT1 expression than patients who were sensitive to it." (PMID 37430272, 2023).
Down syndrome (2 papers, 2016 to 2023). "For example, in sample from donor D4 (carrying Down's syndrome), where MSCs senescence process was delayed, DNMT1 and HDAC1 expression remained higher than in other samples at the same passage (p8)." (PMID 27803714, 2016). "The aim of this study was to investigate the association between the MTHFR rs1801133, MTHFR rs1801131, MTRR rs1801394, DNMT1 rs2228611, DNMT3A rs1550117, DNMT3B rs1569686, and DNMT3B rs2424913 gene polymorphisms and congenital heart defects in Down syndrome (DS) individuals." (PMID 36980848, 2023).
dysplasia (2 papers, 2016 to 2017). A usually neoplastic transformation of the cell, associated with altered architectural tissue patterns. "In addition, we also found higher DNMT1 expression in GC tissues than that in dysplasia tissues in 2 studies with 132 cancers and 76 dysplasia (p < 0.00001)." (PMID 29221215, 2017).
E. coli infection (2 papers, 2022). "Besides, it has also been shown that E. coli infection induced DNMT-1 and DNMT-2 transcription levels and caused differential DNA methylation status of the genome in Manduca sexta and Galleria mellonella." (PMID 35651618, 2022). "Escherichia coli infection regulates the transcription patterns of DNMT-1, and inducing CpG hypermethylation reduces the expression of the cell-cycle inhibitor CDKN2A in human uroepithelial cells." (PMID 35323594, 2022).
erythroleukemia (2 papers, 2014 to 2018). Acute erythroid leukemia characterised by the presence of at least 50% erythroid precursors and at least 20% myeloblasts in the bone marrow. "DNMT1 is overexpressed in Friend Murine Erythroleukemia cells as a result of spontaneous amplification of the Dnmt1 gene in this cell type." (PMID 29482658, 2018). "Studies have reported that DNMT1 gene expression was controlled via transcription factor Fli-1 in erythroleukemia cells, that DNMT1 expression was increased through the JAK-STAT pathway in malignant T lymphocytes, and that AKT activity inhibited DNMT1 degradation in multiple cell lines." (PMID 24675762, 2014).
fibrosis (2 papers, 2023 to 2024). the formation of excess fibrous connective tissue in an organ or tissue in a reparative or reactive process. "In this analysis, hepatic expression of DNMT1, DNMT3a, and DNMT3b was significantly increased in individuals with fibrosis as compared to a control group of healthy individuals." (PMID 38722973, 2024).
gastritis (2 papers, 2022 to 2024). Inflammation of the stomach. "DNMT-1/3A/3B and EZH2 expression were significantly upregulated in Hp-associated gastritis and carcinomas." (PMID 38542354, 2024). "This study investigated the statistical correlation between H. pylori virulence genes and DNMT1 gene expression in gastric antral epithelial cells of gastric adenocarcinoma and gastritis patients." (PMID 36147796, 2022). "The DNMT1 gene expression in gastric adenocarcinoma patients was 3.25-fold higher than in gastritis patients." (PMID 36147796, 2022).
gestational diabetes (2 papers, 2015 to 2023). Carbohydrate intolerance first diagnosed during pregnancy. "In gestational diabetes mellitus (GDM), circHIPK3 blocks miR-1278 to enhance DNMT1 expression and facilitates ferroptosis by inducing NCOA4-mediated ferritinophagy." (PMID 37686142, 2023).
HCMV infection (2 papers, 2020 to 2024). "It was observed that HCMV infection resulted in the re-localization of DNMT1 and DNMT3B from the nucleus in the cytoplasm." (PMID 38314203, 2024).
hepatoblastoma (2 papers, 2017 to 2019). Hepatoblastoma (HB) is a malignant hepatic tumor and is the most common pediatric liver cancer. "Low basal levels of DNMT1 in hepatoblastoma cell lines confirmed an essential role of DNMT1 depletion in the enhancement of cancer stem cell properties." (PMID 29228658, 2017). "It is known that UHRF1/DNMT1 are involved in the maintenance of the hypermethylation of tumor suppressor gene promoters in cancer; in particular, overexpression of UHRF1 was recently reported to silence specific tumor suppressor genes in hepatoblastomas." (PMID 31249594, 2019). "Therefore, it is possible that DNMT1 and DNMT3A upregulation observed in the present study contributes to the hypermethylation at specific CpG islands we previously reported in hepatoblastomas." (PMID 31249594, 2019).
hereditary sensory and autonomic neuropathy type 1 (2 papers, 2022 to 2023). Hereditary sensory neuropathy type I (HSN I) is a slowly progressive neurological disorder characterized by prominent predominantly distal sensory loss, autonomic disturbances, autosomal dominant inheritance, and juvenile or adulthood disease onset. "Hereditary Sensory and Autonomic Neuropathy type 1 (HSAN1) disorder is a neurodevelopmental disorder recently proved to be engendered through mutations in the DNMT1 gene in humans." (PMID 37107631, 2023).
human papillomavirus infection (2 papers, 2022 to 2025). "For example, Laurson reported that human papillomavirus infection induces aberrant host DNA methylation through direct interaction of the viral protein E7 with the DNA methylation enzyme DNMT-1." (PMID 35323594, 2022).
laryngeal carcinoma (2 papers, 2025). Carcinoma that arises from the laryngeal epithelium. "Furthermore, it is the first study investigating expression of DNMT3A and DNMT3B in patients with laryngeal cancer, and it is the first study investigating DNMT1 in locally advanced LSCC." (PMID 40507223, 2025).
laryngeal squamous cell carcinoma (2 papers, 2019 to 2025). A squamous cell carcinoma that arises from the larynx. "Another study demonstrated the role of H19 in larynx squamous cell carcinoma and showed that H19 suppressed the activity of miR-148a-3p, and then enhanced the expression of the target gene DNMT1, which promoted proliferation, migration, and invasion of larynx squamous cell carcinoma cells." (PMID 31632488, 2019).
Leber congenital amaurosis (2 papers, 2024 to 2025). Leber congenital amaurosis (LCA) is a retinal dystrophy defined by blindness and responses to electrophysiological stimulation (Ganzfeld electroretinogram (ERG)) below threshold, associated with severe visual impairment within the first year of life. "In cell cycle (CD−M4), Tubb4b was associated with Leber congenital amaurosis, Dnmt1 with DNMT1 methylopathy, and Diaph3 with auditory neuropathy spectrum disorder." (PMID 39684410, 2024).
lung disease (2 papers, 2017 to 2022). "Because DNMT1 and DNMT3B expression tend to increase in arteries and alveoli, we anticipate total differential methylation occurred in the lungs (including arteries, airway, and alveoli) contributed to the pathogenesis of pulmonary disease." (PMID 36372233, 2022).
lupus nephritis (2 papers, 2019 to 2025). Glomerulonephritis in the context of systemic lupus erythematosus. "The suggestive associations detected between IRFs and epigenetic related factors: DNMT1 and MBD2, encouraged us to explore epigenetic aspects of lupus nephritis, as not only genetic changes may contribute to disease progress." (PMID 31507612, 2019).
malignant glioma (2 papers, 2011 to 2017). A grade III or grade IV glioma arising from the central nervous system. "Together with the well-recognized role of NF2 in glial cell proliferation in some human malignant gliomas, these findings indicated that increased expression of DNMT1 might promote the development of GBM by decreasing the expression of NF2 through methylation." (PMID 28764788, 2017). "Taken together, the significant upregulation of DNMT1 and DNMT3b indicates theirinvolvement in CGI methylation processes in malignant glioma." (PMID 21365007, 2011). "In the current study, we show that in malignant glioma DNMT1 and DNMT3b weresignificantly upregulated, as compared to normal brain." (PMID 21365007, 2011).
mucositis (2 papers, 2023 to 2024). Mucositis is inflammation and damage of the mucous membranes lining the mouth and other parts of the gastrointestinal (GI) tract. "We conclude that the DNMT1 methylation profile is associated with the post-mucositis period and that the genetic and epigenetic profiles of DNMT3A and DNMT3B are associated with creatinine levels." (PMID 37372315, 2023). "In the present study, we found DNMT1 methylation in the group recovered from mucositis, which could be associated with a decrease in its expression since methylation is involved in the regulation of gene expression." (PMID 37372315, 2023). "We conclude that the DNMT1 methylation profile is associated with the post-mucositis period." (PMID 37372315, 2023). "An increase in the methylation frequency for DNMT1 in patients recovered from mucositis was detected." (PMID 37372315, 2023). "For the DNMT1 gene, methylated samples in the post-mucositis group were found, unlike the other groups in which only unmethylated samples were found." (PMID 37372315, 2023).
myocardial ischemia (2 papers, 2021 to 2025). A disorder of cardiac function caused by insufficient blood flow to the muscle tissue of the heart. "In myocardial ischemia/reperfusion injury, HNEAP knockout restores DNMT1-mediated ATF7 methylation, reduces cardiomyocyte death, and improves cardiac function." (PMID 40405297, 2025).
nicotine addiction (2 papers, 2017 to 2022). "Loci associated with nicotine addiction were enriched following overexpression of DNMT1 and DNMTΔ3B3." (PMID 35987848, 2022). "Nicotine can affect gene expression of DNA methyltransferase 1 (DNMT1) that directly or indirectly influences the promoter methylation status of GABAergic neurons, thereby providing a plausible link to nicotine addiction." (PMID 28416970, 2017).
odontogenic tumor (2 papers, 2021). "It has been demonstrated that the high expression of DNMTs in odontogenic tumors’ cells is an important mechanism for their development, in particular the expression of DNMT1 and 3B." (PMID 33680332, 2021). "However, the mean nuclear positivity for DNMT1, DNMT3A, DNMT3B, and H3K9ac, were, respectively, 65.07, 82.03, 39.56, and 88.37%, representing the first report of these proteins in a malignant odontogenic tumor." (PMID 35048062, 2021).
parasite infection (2 papers, 2020 to 2025). "Quantitative RT-PCR analysis revealed that expression levels of DNMT1 were increased by parasite infection." (PMID 31492965, 2020).
prostate adenocarcinoma (2 papers, 2021 to 2023). "In silico RNA sequencing of prostate adenocarcinoma (PRAD) TCGA analysis demonstrated upregulation of DNMT3B, DNMT1, and MBD2 in tumors (n = 497) compared to normal (n = 52) samples, suggesting a global increase in DNA methylation, which might be associated with gene-specific downregulation." (PMID 38201944, 2023).
rectal cancer (2 papers, 2020 to 2023). A primary or metastatic malignant neoplasm that affects the rectum. "Therefore, to further substantiate the results of the bioinformatics analysis, TMAs from patients with rectal cancer were immunohistochemically stained for NSUN4, NSUN7, and DNMT1." (PMID 36911744, 2023). "Furthermore, a cooperation between DNMT1 and DNMT3B was observed in humans; when disrupted, DNA methylation was decrease by 95% in colon rectal cancer cell." (PMID 32614880, 2020).
temporal lobe epilepsy (2 papers, 2016 to 2025). A localization-related (focal) form of epilepsy characterized by recurrent seizures that arise from foci within the temporal lobe, most commonly from its mesial aspect. "On the contrary, it has been shown that Dnmt1 and Dnmt3a expression is increased in the anterior temporal neocortex in human temporal lobe epilepsy." (PMID 27505431, 2016). "Increased expression of DNMT1 and DNMT3A has been demonstrated in epileptic model and patients with temporal lobe epilepsy." (PMID 40534269, 2025).
thymic neoplasm (2 papers, 2016 to 2020). "To further address this issue, we analyzed DNA methylation levels of genes involved in one-carbon metabolism (MTHFR) and DNA methylation (DNMT1, DNMT3A, and DNMT3B) in blood, tumor tissue, and healthy thymic epithelial cells from MG patients that underwent a surgical resection of a thymic neoplasm." (PMID 27999265, 2016).
thyroid tumor (2 papers, 2024 to 2025). A benign or malignant neoplasm affecting the thyroid gland. "Further studies were focused on the connection between global and local DNA methylation status, and the assessment of levels of DNA methylation regulators (TET family and DNMT1) in thyroid tumors." (PMID 41150811, 2025).
Uterine leiomyoma (2 papers, 2012 to 2021). The presence of a leiomyoma of the uterus. "DNMT1 gene expression was higher in uterine leiomyoma vs myometrium." (PMID 34233687, 2021).
Zinc deficiency (2 papers, 2021 to 2022). A deficiency of the essential metal Zinc; an essential cofactor for many enzymes. "Furthermore, a prior work discovered that DNMT1 upregulation was involved in cognitive dysfunction induced by zinc deficiency in rats." (PMID 35710537, 2022). "One possible mechanism by which zinc deficiency could upregulate DNMT1 activity is by distorting the N-terminal CXXC domain’s integrity due to lack of zinc, which may result in loss of its autoinhibitory function." (PMID 33652690, 2021). "Moreover, in another study on hypozincemia-induced cognitive dysfunction in rats, zinc deficiency led to the upregulation of DNMT1 transcription in their hippocampus and subsequent hypermethylation of the brain-derived neurotrophic factor (BDNF) gene and its downregulation." (PMID 33652690, 2021). "For instance, studies have shown a significant increase in the protein expression levels and activities of DNMT1 and DNMT3A in zinc-deficient human esophageal cancer (EC) cell lines compared to similar cell lines without zinc deficiency." (PMID 33652690, 2021).
adrenocortical tumor (1 paper, 2022). "Reduction of Dnmt1 expression in a murine adrenocortical tumor cell line induces DNA demethylation and inhibits tumorigenesis." (PMID 36329185, 2022).
age (1 paper, 2022). A temporal measurement of the time period elapsed since an identifiable point in the life cycle of an organism. "Further studies are required to investigate the anti-osteogenic and anti-chondrogenic mechanism of DNMT1 in detail, and to evaluate the effectiveness of DNMT1-specific inhibitors, such as MG98, in the prevention and treatment of age-related bone loss in animal models." (PMID 35238333, 2022).
amyotrophic lateral sclerosis 4 (1 paper, 2024). "Also, in patients with amyotrophic lateral sclerosis 4 (ALS4), caused by mutations in senataxin, R-loops have been shown to block DNA methylation at gene promoters and inhibit DNA methyl-transferase-1 (DNMT1) activity leading to activation of the TGFb pathway." (PMID 39342995, 2024).
anaplastic astrocytoma (1 paper, 2012). "However, the epigenetic inactivation of DNMT1 gene plays a part in the pathogenesis of anaplastic astrocytoma progression." (PMID 22264301, 2012).
BAFopathies (1 paper, 2023). "Expectedly, a few cases of disorders with related episignatures came up such as a DNMT1-deficient sample in case of the KMT2B classifier and samples from BAFopathies or Kabuki type 2 in case of the KMT2D classifier." (PMID 37365401, 2023).
bowel cancer (1 paper, 2021).
cholestasis (1 paper, 2017). Impairment of the bile flow caused by obstruction within the liver, or outside the liver in the bile duct system. "In the BDL-miR-29aTg group, the abundances of DNMT1, DNMT3b and SET1A were significantly lower than those in the BDL-WT group (p < 0.001, respectively), which was suggestive of the active responses of these molecules to miR-29a signaling in early cholestasis." (PMID 28106784, 2017).
choriocarcinoma (1 paper, 2021). An aggressive malignant tumor arising from trophoblastic cells. "Besides, DNMT1 and DNMT3b were negatively correlated with miR-497-5p in eight choriocarcinoma tissues." (PMID 34732693, 2021).
chronic asthma (1 paper, 2021). An asthma that is characterized by the development of persistent airway inflammation and recurrent attacks of breathlessness and wheezing, which vary in severity and frequency. "We measured the expression of DNA methyltransferase and found that the expression of DNMT3a and DNMT3b were significantly decreased in chronic asthma while DNMT1 did not have any statistical difference." (PMID 35058921, 2021).
congestive heart failure (1 paper, 2025). Failure of the heart to pump a sufficient amount of blood to meet the needs of the body tissues, resulting in tissue congestion and edema. "The congestive heart failure-associated targets were Dnmt1, Hdac1, Hdac4, Ezh2, Sirt3, Kdm2a, Prkca and Prkcb (9.8% of total targets)." (PMID 40076868, 2025).
diabetic foot ulcer (1 paper, 2025). "The Wilms tumor 1-associated protein (WTAP)-DNA methyltransferase 1 (DNMT1) axis acts as a pivotal regulator of diabetic foot ulcer healing." (PMID 40943661, 2025).